SCN1A (sodium voltage-gated channel alpha subunit 1)
Diseases named in the same sentence as SCN1A in open-access papers (continued):
Sharing a sentence is not in itself a finding about the gene and the disease.
epilepsy (continued). "SCN1A has been intensively studied regarding the risk of epilepsy." (PMID 35801810, 2022). "The pivotal involvement of inhibitory interneurons in epilepsy was also shown in studies based on iPSCs models of pathogenic SCN1A mutations; others have instead demonstrated the involvement of both glutamatergic and GABAergic populations in the epileptic brain hyperexcitability." (PMID 35625812, 2022). "However, DS is mainly caused by SCN1A gene mutation, which belongs to “whole brain” epilepsy, resulting in over-excitability of the whole brain region without obvious focal lesions, and does not belong to the surgical indication for focal resection." (PMID 35493838, 2022). "SCN2A and SCN1A, two genes detected in the current fetus, are known to be associated with epilepsy." (PMID 35819063, 2022). "We also discovered that in SCN1A gene, the variant genotypes of rs6432861 (CC) may influence the risk of epilepsy according to this study outcomes." (PMID 35801810, 2022). "In addition to ASD, proband MC-17-3 presented with epilepsy, the characteristic phenotype in patients with SCN1A loss of function mutations." (PMID 35190550, 2022). "The proband with an SCN1A seizure disorder has almost 50% pathogenic variant from parents." (PMID 35813387, 2022). "Seven patients with SCN1A-related epilepsy had seven different SCN1A variants (NM_001165963.4)." (PMID 36237607, 2022). "SCN1A, a sodium channel present in both excitatory and inhibitory neurons, is of particular relevance to epilepsy given that 80% of patients with Dravet syndrome, which presents with severe epilepsy in children, have loss of function SCN1A mutations." (PMID 35874848, 2022). "We suggest that TT genotype of rs3812718 in SCN1A may be a protective factor against epilepsy and may decrease the risk of the disease in Saudi population." (PMID 35801810, 2022). "Scn1a gene disruption leads to the development of seizures, often associated with sudden unexpected death in epilepsy (SUDEP) and behavioral alterations including hyperactivity, social interaction deficits and cognitive impairment starting from the second/third week of age." (PMID 35013317, 2022). "Of particular relevance in adolescent use, some involve, though not limited to, GPR55 in epilepsies resulting from heterozygous mutation to the Scn1a gene, 5-HT1a receptors in anxiety, depression, and protection against acute stressors, and PPARs and TRPV receptors on digestive and gut health." (PMID 34512286, 2021). "Children affected with SCN1A loss-of-function mutations experience frequent prolonged spontaneous seizures, developmental delays, cognitive and behavioural deficits as well as increased risk of Sudden Unexpected Death in Epilepsy." (PMID 33842883, 2021). "While phenotypes were less severe in heterozygous 1b+/− mice, presence of temperature and PTZ-induced behavioral seizures and elevated observations of epileptiform indices in EEG in these mice indicate a milder phenotype with relevance to SCN1A-associated epilepsies." (PMID 33910599, 2021). "The paper titled “Seizure phenotype and underlying cellular defects in Drosophila knock-in models of DS (R1648C) and GEFS+ (R1648H) SCN1A epilepsy” is focused on characterizing two mutations at the same position in SCN1A, R1648C and R1648H, and their role in epilepsy." (PMID 34475263, 2021). "Regions of SCN1A with functionally validated epilepsy variants with references." (PMID 33841294, 2021). "In fact, amongst all epilepsy genes, SCN1A mutations are the most implicated." (PMID 33841294, 2021). "While SCN1A-associated epilepsy is typically considered a loss-of-function disease, our results put L1624Q into a growing set of mixed gain and loss-of-function variants in SCN1A responsible for epilepsy." (PMID 34925043, 2021).
epilepsy (continued). "Previous work, including a knock-in mouse model for a mild epilepsy carrying a neighboring SCN1A mutation to L1649Q (R1648H), revealed opposite effects to those observed here, i.e. a loss-of-function of Na+ currents and a decreased firing rate of inhibitory interneurons." (PMID 34546973, 2021). "Over 1,200 SCN1A distinct variants have been associated with epilepsy." (PMID 34925043, 2021). "However, biophysical analysis has revealed a significant subset of missense mutations that result in increased excitability, further complicating approaches to precision pharmacotherapy for patients with SCN1A variants and epilepsy." (PMID 34925043, 2021). "Thermal-evoked seizures are a hallmark of DS and SCN1A-associated epilepsy models, and thus, we tested whether these were induced in 1b+/− mice." (PMID 33910599, 2021). "In fact, GEFS+ and DS are different manifestations of epilepsy caused by SCN1A mutations." (PMID 35002916, 2021). "Mutations in SCN1A are associated with epilepsy, including Dravet syndrome (DS)." (PMID 33910599, 2021). "The results indicate that patients of Asian descent with epilepsy and SCN1A polymorphism rs2298771, especially with the GG genotype, may be at risk of CBZ resistance." (PMID 34769124, 2021). "Further, genome-wide association studies (GWAS) have implicated non-coding SCN1A DNA variants as contributing to epilepsy risk, presumably via more subtle perturbation to transcriptional regulation, and non-coding promoter deletions have been found in DS patients." (PMID 33910599, 2021). "SCN1A-associated epilepsies, including DS, remain difficult to treat as conventional sodium channel blockers are usually ineffective and may even exacerbate the disease." (PMID 33910599, 2021). "It is interesting to note that mutations in Scn1a have been proposed to contribute to cardiac arrhythmias and sudden unexpected death in epilepsy (SUDEP) based on studies in mice, but the relative roles played by direct and indirect mechanisms are not yet clear." (PMID 33411788, 2021). "Monoallelic variation of the alpha subunit of the sodium channel (SCN1A) gene is a well-established cause of a spectrum of seizure disorders that include simple febrile seizures, febrile seizures plus (FS+) and genetic epilepsy with febrile seizures plus (GEFS+)." (PMID 33216760, 2020). "Here, we investigate the presence of rare and more common variants in epilepsy‐related genes that could potentially modify disease severity, in a cohort of 87 patients with SCN1A‐related epilepsy." (PMID 32032478, 2020). "In addition, Scn1a KO deficiency exacerbates the typical pathological manifestations of epilepsy in Scn1a KO mice." (PMID 32184723, 2020). "Variants in SCN1A are associated with a wide range of epilepsy phenotypes." (PMID 32783192, 2020). "An example of sperm aging HyperDMR (chr2:166900333–166900544) is overlapping exon 11 of SCN1A, most common genetic cause of epilepsy, intriguingly most de novo mutations arise in the paternal chromosome, but paternal age has not yet been associated with occurrence of mutations." (PMID 33317634, 2020). "Mutations in Na channel genes have been extensively linked to epilepsy; however, Okamura’s group have reported a link between a novel SCN1A mutation (V1366I) in a Japanese family with different mental illness phenotypes including Asperger syndrome, ASD and panic disorder." (PMID 33375447, 2020). "Indeed, subsequent WES analysis of this patient revealed pathological de novo mutation in the SMC1A gene (data not shown), hence the functional study of this variant indicated the misdiagnosed problem of SCN1A-related epilepsies." (PMID 32581296, 2020). "Relatively common variants in epilepsy genes may play a large role in modulating SCN1A‐related phenotypes." (PMID 32032478, 2020). "Epilepsies associated with SCN1A mutations exhibit extraordinary clinical heterogeneity." (PMID 30705357, 2019). "A total of three mutations were identified in known epilepsy genes (SCN1A, SCN2A)." (PMID 31439038, 2019).
epilepsy (continued). "Interestingly, in Dravet syndrome, a severe encephalopathy due to de novo loss-of-function mutations in the SCN1A gene, leading to haploinsufficiency of NaV1.1 channel, epilepsy typically presents around 6 months of age." (PMID 30983952, 2019). "Notably, 35.4% of patients in our cohort had SCN1A mutations, which have been previously associated with a spectrum of seizure disorders." (PMID 31031587, 2019). "For instance, it has been found that missense alterations in the gene that encodes the NaV1.1 (SCN1A) may lead to serious severe epilepsy in infants due to imperfections at the level of the AIS." (PMID 31933626, 2019). "The genetic etiology of epilepsy may be monogenic, resulting from single gene mutations (e.g., SCN1A mutations in Dravet syndrome)." (PMID 29467791, 2018). "All these findings show how treatment response maybe specific to the nature and the location of the SCN1A mutation, and offers up a somewhat daunting perspective of precision medicine in the epilepsies." (PMID 28082152, 2018). "Similarly, SCN1A missense variants often segregate in families in which there are members with DS, milder forms of epilepsy, and unaffected carriers." (PMID 28686619, 2017). "Among their pharmacological effects, some AEDs may block voltage-dependent sodium channels, which stimulate the researchers to investigate the potential link between drug-resistant epilepsy and polymorphisms in channels genes like SCN1A gene." (PMID 28202008, 2017). "Most affected individuals are sporadic cases without affected family members; however, there are known examples of families in which an SCN1A truncation mutation is transmitted through multiple generations, with some members exhibiting typical DS, and others with milder epilepsy." (PMID 28686619, 2017). "Indeed, one of the associations reported by the all epilepsy GWAS meta-analysis was with SCN1A, which is implicated in some monogenic epilepsies and is targeted by a number of conventional antiepileptic drugs." (PMID 28334860, 2017). "The following, yet incomplete, hypothesis emerges regarding the pharmacological profile of FA that underlies the treatment of DS and possibly other SCN1A-related epilepsies." (PMID 28428755, 2017). "Our results showed that the significantly changed neuronal subtype is GABAergic neurons, which suggested that the selection of GABA analog is a more niche-targeting strategy to treat epilepsy in this patient's family as well as in other patients with SCN1A loss-of-function." (PMID 26731440, 2016). "After combining our in-house control and ExAc data in a meta-analysis, only the p.T1174S variant remained significantly enriched after correction for multiple testing in epilepsy patients supporting p.T1174S as the only identified SCN1A genetic risk factor for epilepsy in our cohort." (PMID 26990884, 2016). "The role of SCN1A missense mutations in the pathogenesis of common epilepsies may thus be overstated (in general and e." (PMID 26990884, 2016). "Dravet syndrome is the prototype of SCN1A-mutation associated epilepsies." (PMID 27582020, 2016). "We identified seven out of 777 epilepsy patients (0.90%) carrying the p.T1174S SCN1A mutation." (PMID 26990884, 2016). "We present a patient with an early-onset, temperature-sensitive epilepsy phenotype and a heretofore uncharacterised de novo heterozygous SCN1A mutation (c.3818C > T, ClinVar Accession: RCV000180969.1) coding for a mutant in DIIIS2 of the NaV1.1 channel (p.Ala1273Val)." (PMID 27582020, 2016). "The SCN1A IVS5-91G>A SNP is associated with susceptibility to epilepsy." (PMID 26555147, 2015). "Genotyping these two SNPs in epileptic patients and healthy controls revealed that carriers of the SCN1A IVS5-91G>A variant were at increased risk of epilepsy susceptibility (P = 0.033; OR 1.80, 95% CI 1.048, 3.094), while no impact for SCN1A c.3184A>G SNP was observed." (PMID 26555147, 2015).
epilepsy (continued). "Furthermore, SCN1A alleles have also been recognized to cause autism and epilepsy phenotypes together with biopsy-proven mitochondrial disease." (PMID 24204377, 2013). "Ranalozine proved also ability to cross the blood-brain barrier while tested in rats, which together with inhibition of persistent current in mutant NaV1.1 channels give rise for possible providing a new useful therapeutic strategy for SCN1A-associated epilepsy and some migraine syndroms." (PMID 23409712, 2013). "SCN1A mutation is therefore a key factor of cognitive delay, in addition to epilepsy." (PMID 24225340, 2013). "We studied the correlation between DQ/IQ/SQPS and age, epilepsy characteristics, and whether patients presented SCN1A mutation." (PMID 24225340, 2013). "Additional support for discrete phenotypes resulting from the same ion channel protein comes from the identification of SCN1A mutations in either epilepsy or familial hemiplegic migraine, and CACNA1A mutations in familial hemiplegic migraine, episodic ataxia and spinocerebellar ataxia." (PMID 19763161, 2009). "Indeed, genetic analyses conducted in SUDEP cases have revealed the presence of potentially dangerous genetic alterations in genes involved in the control of cardiac rhythm (such as KCNQ1) and in genes associated with severe forms of epilepsy (such as SCN1A and DEPDC5)." (PMID 41062843, 2026). "Mutations such as truncations or missense mutations in the SCN1A gene, which encodes the αsubunit of the Nav1.1 channel, can lead to Dravet syndrome, SCN1A mutations are frequently associated with a spectrum of clinical manifestations, including epilepsy, autism, and intellectual disability." (PMID 40667464, 2025). "SCN1A, the gene encoding for the Nav1.1 channel, exhibits dominant interneuron-specific expression, whereby variants disrupting the channel’s function affect the initiation and propagation of action potentials and neuronal excitability causing various types of epilepsy." (PMID 38891831, 2024). "Seizure disorders in Dravet syndrome mouse models caused by mutations in the Scn1a gene are accompanied by disturbances in GABAergic firing in hippocampal neurons, which may also indicate attenuation of epileptiform behavior due to Sigma1R-dependent modulation of GABAARs activity." (PMID 37298532, 2023). "Therefore, polymorphisms of the SCN1A gene could play a role in the response to AED in patients with drug-resistant epilepsy, with important implications for clinical practice." (PMID 37628333, 2023). "Similarly to FHM2, epilepsy with SCN1A mutations is very common." (PMID 37628876, 2023). "In addition, SCN1A was involved in Dravet syndrome (DS) which is severe genetic epileptic encephalopathy with an increased risk of sudden and unexpected death of someone with epilepsy." (PMID 35801810, 2022). "De novo loss-of-function mutations in the VGSC SCN1A (encoding Nav1.1) are the main cause of Dravet syndrome (DS), a catastrophic early-life encephalopathy associated with prolonged and recurrent early-life febrile seizures, refractory afebrile epilepsy, and behavioral deficits." (PMID 35153788, 2022). "Thus far, the SCN1A locus is the most replicated genetic risk factor found in epilepsy." (PMID 34573423, 2021). "Furthermore, haploinsuficiency of RYR3 might cooperate in an indirect way with several membrane proteins coded by genes implicated in sodium or calcium voltage channels, including SCN1A that is also implicated in epilepsy." (PMID 33557955, 2021). "Notable examples of this include the SCN1A-associated seizure disorders where commonly used sodium-channel-blocking medications carbamazepine, vigabatrin and lamotrigine should be avoided because they may worsen the condition by inducing and/or prolonging seizures." (PMID 33216760, 2020). "Similarly, DS was common in epilepsy with ASD patients due to SCN1A gene mutations." (PMID 31139143, 2019).
epilepsy (continued). "Moreover, as multiple DNA regions can be mutated within the same gene, it is likely that the SCN1A mutation can be identified in multiple kinds of genetic epilepsies, including severe myoclonic epilepsy of infancy, epilepsy with febrile seizures plus, and partial epilepsy with febrile seizures plus." (PMID 31185666, 2019). "Our data indicate that, while currently available bioinformatics tools are insufficient for predicting the severity of epilepsy and cognitive outcome, functional studies in mammalian expression systems may foretell the severity of de novo SCN1A missense mutations." (PMID 30735520, 2019). "Common variants in SCN1A have been associated with mesial temporal lobe epilepsy and hippocampal sclerosis with febrile seizures in a genome-wide association study, and in a recent meta-analysis including 8696 patients with genetic generalized-, focal-, or unclassified epilepsies." (PMID 26990884, 2016). "Therefore, the SCN1A A/A genotype may be associated with treatment-resistant epilepsy in patients administered VPA due to the different expression levels of the neonatal and adult isoforms." (PMID 26484865, 2015). "Increases in genetic testing have prompted numerous reports identifying four VGSC genes of significant clinical importance in epilepsy: SCN1A, SCN2A, SCN3A, and SCN8A." (PMID 41007641, 2025). "MRI in SCN1A-related epilepsies, including Dravet syndrome, has historically been reported as normal, especially in early life." (PMID 41573391, 2025). "Beyond TSC2 and SCN1A patients, who, as expected, demonstrated high seizure reduction rates, other monogenic epilepsies also showed favorable responses." (PMID 40126049, 2025). "MCD was detected in patients with SCN2A-related epilepsy (2/17, 11.8%) and SCN1A-related epilepsy (1/114, 0.9%)." (PMID 41573391, 2025). "SCN1A-related epilepsies, particularly Dravet syndrome, have well-established therapeutic guidelines." (PMID 40903466, 2025). "This case illustrates the potential for adult-onset phenotypic progression in SCN1A-related epilepsy and expands the spectrum of late-onset manifestations associated with DS." (PMID 41158906, 2025). "For example, Clemizole was initially identified in an SCN1A-mutant zebrafish epilepsy model as an anti-seizure compound and was later validated in vitro to act via the 5-HT2B receptor." (PMID 41516158, 2025). "Historically, brain MRI findings in SCN1A-related epilepsies, particularly Dravet syndrome, have often been reported to be normal." (PMID 41573391, 2025). "For other epilepsies with a marked phenotypic heterogeneity, for example, SCN1A‐related epilepsies, the relevance of additional genomic variation (beyond SCN1A) has been shown." (PMID 40207589, 2025). "The mammalian genome encodes nine distinct VGSC subtypes, and mutations in several of these—particularly SCN1A, SCN2A, and SCN8A—are strongly linked to specific forms of epilepsy." (PMID 41282053, 2025). "Using epilepsy panels and WES, we identified rare variants in several genes, including POLG, SCN1A, SCN9A, KIF1A, and CNTNAP2, which were associated with specific clinical characteristics." (PMID 40565516, 2025). "For example, Dravet syndrome (DS) is a type of monogenic epilepsy, a DEE associated with monoallelic loss-of-function mutations in the SCN1A gene." (PMID 39937026, 2025). "Exome sequencing identifies rare variants in epilepsy-associated genes (e.g., DEPDC5, CHD2) enriched in DS patients, with SCN1A-DEPDC5 co-mutations often associated with focal cortical dysplasia." (PMID 40772259, 2025). "Some of the well-known mouse models of epilepsy include constitutive knockout of channel proteins such as SCN1A, SCN2A, SCN8A, KCNA1, GABRA1, KCNQ2, and many more." (PMID 40529445, 2025).